SENP8 (SUMO peptidase family member, NEDD8 specific)
Synonyms: DEN1; NEDP1; PRSC2; HsT17512
Tractability: Small molecule: it belongs to a druggable protein family. PROTAC: a small molecule that binds it is known.
Target class: Protease; Enzyme; Cysteine protease CE clan; Cysteine protease C48 family; Cysteine protease
Gene: Protein-coding gene on chromosome 15 (72,114,258 to 72,143,692, forward strand). Ensembl gene ENSG00000166192.
Subcellular location (Human Protein Atlas): Nucleoplasm; Vesicles
Pathways (Reactome):
Metabolism of proteins: Neddylation; UCH proteinases
Gene Ontology:
Molecular function: protein binding; deNEDDylase activity; cysteine-type peptidase activity
Biological process: post-translational protein modification; protein deneddylation; protein deubiquitination; proteolysis
Cellular component: cytosol
Genetic constraint (gnomAD): Loss-of-function variants: 9 observed, 14.93 expected, observed/expected ratio (o/e) 0.6, 90% interval 0.36 to 1.05. The upper end of that interval is the gene's LOEUF score, 1.05, which puts it in group 4 of 6, group 1 being the genes least tolerant of losing a copy. Missense variants: 195 observed, 255.98 expected, observed/expected ratio (o/e) 0.76, 90% interval 0.68 to 0.86. Synonymous variants: 91 observed, 97.83 expected, observed/expected ratio (o/e) 0.93, 90% interval 0.78 to 1.11.
Homologues: Orthologues: chimpanzee SENP8 (99% identical), macaque SENP8 (97% identical), dog SENP8 (95% identical), pig SENP8 (94% identical), mouse Senp8 (92% identical), rat Senp8 (92% identical), rabbit SENP8 (89% identical), zebrafish senp8 (62% identical), tropical clawed frog senp8 (50% identical), Drosophila melanogaster Den1 (36% identical), Caenorhabditis elegans ulp-3 (27% identical), Drosophila melanogaster CG1503 (25% identical). Paralogues in human: FAM76A (15% identical), FAM76B (15% identical).
Diseases named in the same sentence as SENP8 in open-access papers:
SENP8 is named in the same sentence as 16 diseases in open-access papers, as found by Europe PMC text mining. Sharing a sentence is not in itself a finding about the gene and the disease. The quoted sentences say what the papers report.
colon cancer (2 papers, 2023 to 2026). "Deneddylation of SHP2 by sentrin-specific protease 8 (SENP8) inactivates αMβ2 integrin, ultimately impairing macrophage phagocytosis in colon cancer." (PMID 41540013, 2026). "Immunosuppressive TIMs in human colon cancer tissue were further identified as related to SENP8 using stained paraffin slides." (PMID 36626230, 2023).
cataract (1 paper, 2020). Partial or complete opacity of the crystalline lens of one or both eyes that decreases visual acuity and eventually results in blindness. "Also, male cataract patients had higher levels of SENP3, SENP7, and SENP8 than female patients." (PMID 32827359, 2020).
colon adenocarcinoma (1 paper, 2023). "Most interestingly, we identified two MALAT1-dependent novel molecules, ZNF638 and SENP8, that are associated with significant alterations in colon adenocarcinoma patients’ overall survival and disease-free survival." (PMID 37325561, 2023). "In addition, two of the MALAT1 targets shared across the small intestine and colon, ZNF638 and SENP8, are associated with a change in hazards ratio for overall survival and disease-free survival in human colon adenocarcinoma patients." (PMID 37325561, 2023).
colon adenoma (1 paper, 2023). An adenoma that arises from the colon. "Among the 30 MALAT1-targets shared by both the small intestine and colon, ZNF638 and SENP8 levels are predictive of colon adenoma patient overall survival and disease-free survival." (PMID 37325561, 2023).
Leigh syndrome (1 paper, 2024). A progressive neurological disease defined by specific neuropathological features associating brainstem and basal ganglia lesions. "PNE also caused the downregulation of Senp8, which is involved in neural development, and Coa4 which encodes a cytochrome c oxidase (COX) assembly factor whose downregulation may be linked to Leigh Syndrome or other related neurological disorders." (PMID 39574597, 2024).
renal clear cell carcinoma (1 paper, 2020). "SENP8 and PIAS1 play protective roles in renal clear cell carcinoma." (PMID 33123273, 2020).
rheumatoid arthritis (1 paper, 2023). A chronic, systemic autoimmune disorder characterized by inflammation in the synovial membranes and articular surfaces. "In mice, NFIC regulates the expression of PTEN/SENP8 and inhibits rheumatoid arthritis-induced inflammation." (PMID 37244954, 2023).
tumor (6 papers, 2009 to 2023). "Not surprisingly, multiplex IHC (mIHC) validated more profound pERK inhibition as well as increased cleaved caspase-3 signal in tumors from Senp8mφ–/– mice under anti-PDL1 treatment, and SENP8 deficiency promoted M1 polarization of TIMs in tumor infiltrates." (PMID 36626230, 2023). "Of note, SENP8 deficiency enhanced the effect of PDL1 blockade on inhibition of tumor growth, which was accompanied by a marked increase in survival." (PMID 36626230, 2023). "To provide additional support for SENP8 deficiency in a macrophage-reshaping tumor microenvironment, we also surveyed the composition of chemokines and cytokines." (PMID 36626230, 2023). "Interestingly, UHRF1 has been shown to bind to the methylated promoter region of the p14ARF tumor suppressor, which we also found was significantly downregulated in SENP8-deficient cells." (PMID 28475037, 2017). "3D rendering data demonstrated morphologically stronger nuclei transformation of opsonized tumor cells internalized by Senp8+/– BMDMs." (PMID 36626230, 2023). "SENP8 regulates deneddylation in TIMs to respond to tumor cell CD47." (PMID 36626230, 2023). "In addition, catalytic cysteines of SENP8 have been reported to be sensitive to ROS, which dynamically influence the tumor microenvironment." (PMID 36626230, 2023). "Although neddylation activation of Cullin-RING ubiquitin ligases for tumor cell survival is well established, increased non-Cullin substrates have been proposed as performing a wide variety of functions, in which the deconjugation cycle is specifically modulated by deneddylase SENP8." (PMID 36626230, 2023).
SENP8 also shares sentences with these, for which no sentence is quoted: dengue (10 papers); infection (3); amyotrophic lateral sclerosis (1); breast carcinoma (1); cancer (1); hepatocellular carcinoma (1); neurodegenerative disease (1); neurological disorders (1).